IRS1 (insulin receptor substrate 1)
Diseases named in the same sentence as IRS1 in open-access papers (continued):
Sharing a sentence is not in itself a finding about the gene and the disease.
tumor (continued). "Although the major biological function of PTEN is to dephosphorylate lipid substrates, it has also been reported to dephosphorylate protein substrates, including cAMP-responsive element-binding protein 1 (CREB1) and insulin receptor substrate 1 (IRS1) to perform its tumor-suppressive function." (PMID 36336681, 2022). "NE could penetrate into tumor cells and degrade insulin receptor substrate-1, which led to the enhancement of tumor cell proliferation via the PI3K axis." (PMID 36555469, 2022). "Our studies suggest that routine targeting of activated PRs as part of ER-targeted therapies may prevent relapse of ER+ tumours by disruption of ER/PR/IRS-1 complexes." (PMID 33144693, 2021). "Importantly, Herceptin in combination with specific knockdown of IRS1 led to a sustained and significant inhibition on tumor growth and dramatically reduced tumor sizes and weights." (PMID 33976188, 2021). "Importantly, scRNAseq identified PGR and IRS-1 enrichment in metastases compared to primary tumours, whereas IGF1R expression trended downward in metastases." (PMID 33144693, 2021). "Additionally, overexpression of miR-148a targets IGF-IR and IRS1 suppresses BC cells proliferation and tumor angiogenesis by suppressing their downstream AKT and MAPK/ERK pathways." (PMID 34778378, 2021). "Furthermore, tumor proliferation is mediated by the degradation of insulin receptor substrate 1 (IRS1) by neutrophil elastase and the activation of PI3K signaling." (PMID 34048186, 2021). "Neutrophils can also mediate and facilitate tumor proliferation by attenuating the immune system and via degradation of insulin receptor substrate 1 and the activation of phosphoinositide 3-kinase signaling as a result of the transfer of neutrophil elastase to cancer cells." (PMID 33215031, 2020). "In addition, miR-145 shows tumor-suppressing activity by inhibiting several genes, including c-Myc, IRS1, MUC1, and FASCN1." (PMID 32906592, 2020). "IRS-1 may maintain differentiation and prevent tumor invasion by impeding the epithelial mesenchymal transition (EMT)." (PMID 31393907, 2019). "The tumour-bearing group had increased serum WF content, and the skeletal-muscle showed a reduction in IRS-1 and RAG activation, increased PKB/Akt and Erk/MAP4K3 on the 21st day, and maintenance of p70S6K1, associated with increases in muscle STAT-3 and STAT-6 levels in these tumour-bearing rats." (PMID 30975087, 2019). "Some of the more well described targets are SPRED1, p85β, and PI3KR2 governing vascular integrity, VEGF-A regulating AKT-pathway signaling, CXCR4 and IRS-1 involved in CRC cell proliferation and migration, and KRAS impacting on the viability of the mutated tumor cells." (PMID 35582589, 2019). "Overexpression of insulin receptor substrate 1 (IRS-1) is known to reduce tumor growth." (PMID 31474975, 2019). "“NE induces tumor cell proliferation by NE insulin receptor substrate-1 (IRS-1) degradation." (PMID 31799175, 2019). "Given the ability of IRS-1 to inhibit tumor progression, our finding suggests that alternative mechanisms for suppressing IRS-1 function, rather than expression, may occur in these tumors." (PMID 31393907, 2019). "Coherently, ΔNp63 and IRS1 expression patterns are positively correlated in primary tumours, suggesting that the interaction of p63 and IRS1 might contribute to the pathogenesis of HNSCC." (PMID 30594912, 2018). "Lower levels of IRS-1 were associated with an increase in the interaction between phosphatidylinositol 3-kinase (PI3K) and the potent mitogen platelet-derived growth factor receptor (PDGFR), which directed the PI3K axis to favour tumour proliferation." (PMID 30137312, 2018). "In addition tumor proliferation can be mediated by degradation of the insulin receptor substrate 1 (IRS1), and activation of PI3K signaling due to the transfer of neutrophil elastase to cancer cells." (PMID 28810877, 2017). "Tumor suppressor microRNA, miR-145, has been shown to downregulate IRS-1 expression in the colon." (PMID 28414818, 2017).
tumor (continued). "Previously, IRS-1 was reported to be targeted by miR-126 in tumor cells." (PMID 28253326, 2017). "On the other hand, knockdown of IRS-1 leads to reduced cell migration and decreased tumor growth." (PMID 28414818, 2017). "Overexpression of IRS1 in cells promoted cell transformation and in mice lead to tumor development." (PMID 27203214, 2016). "Similarly, MIR126 was found to suppress tumours by directly targeting the insulin receptor substrate-1 (IRS1) and the disintegrin- and metalloproteinase domain-containing protein-9 (ADAM9)." (PMID 27119351, 2016). "This is probably related to the activation of feedback compensatory loops leading to tumor cell resistance like the up-regulation of IRS-1 protein levels and the induction of IRS-1 phosphorylation, the activation of both Akt phosphorylation via mTORC2 and MAPK pathway via S6K/PI3K/Ras pathway." (PMID 26756219, 2016). "Similarly to INSR, the mRNA expression of IRS1 is decreased in the tumour tissue compared to that in the control tissue (FDR = 2.62E-10)." (PMID 25496518, 2014). "This was exemplified by Irs1 and Pik3r1 (p85) in PyMT tumours." (PMID 25200860, 2014). "Among the upregulated genes, we identified several oncogenes (Ets2, Fyn, Fos, Rab30 and Src), various tumor markers (Cyp1b1, Gpa33, Cd47, Fam129a, st7l, chka, Lgalsbp, Antxr1 and Ly6a) and other genes related to tumor promotion (Cxcl10, Trim25, Grn, Foxc2, Bmp7 and Irs1)." (PMID 23936067, 2013). "NE enters tumor cell endosomes, degrading insulin receptor substrate-1 and releasing PI3Kp85." (PMID 23272179, 2012). "IRS1 loss and IRS2 accumulation may represent important mechanism underlying AFB1-induced tumor progression." (PMID 23112878, 2012). "Further studies are needed to verify whether IRS1 concurs in identifying CRCs that, independently of classic pathological variables, have poor prognosis because of selective advantages during tumor progression." (PMID 22558377, 2012). "Thus, our findings afford a credible explanation for IRS-1 involvement in the tumor initiation and progression." (PMID 22788551, 2012). "IRS1 deficient tumor cells are more invasive, while IRS2 deficient tumor cells are less invasive." (PMID 23112878, 2012). "Our data afford a plausible explanation for IRS-1 involvement in tumor initiation and progression." (PMID 22788551, 2012). "Interestingly, total membrane and cytoplasmic erbB3 expression was significantly higher in phosphorylated membrane IRS-1 Y612-positive tumours than in phosphorylated membrane IRS-1 Y612-negative tumours (P = 0.009 (n = 33))." (PMID 21939528, 2011). "IRS-1-dependent signals also contribute to tumor cell survival." (PMID 19534786, 2009). "In contrast with the positive role for IRS-1 in early tumor development and growth, IRS-1 may play a suppressive role in tumor progression." (PMID 19534786, 2009). "Importantly, suppression of Irs-2 expression in Irs1-/- tumor cells restores mTor activation to wildtype levels, confirming the contribution of Irs-2 to the increased mTor activity." (PMID 19534786, 2009). "Indeed, incorporation of TRS1 and IRS1 into the attenuated Δγ134.5 virus produced a more robust vector, permitting more efficient destruction of tumor cells and resulting in enhanced anti-tumor activity." (PMID 21994558, 2009). "One potential mechanism for IRS-specific regulation of tumor cell functions is the recruitment of effectors to unique binding motifs in the C-termini of the IRS proteins that activate signaling pathways selectively downstream of either IRS-1 or IRS-2." (PMID 19534786, 2009). "By coupling IGF-IR activation to proliferative pathways, expression of IRS-1 could identify tumours that are most likely to respond to IGF-IR inhibition." (PMID 17043687, 2006). "Furthermore, IRS1 promotes the transcription of the tumor stem cell marker SALL4, suggesting that it might be implicated in the stemness property of CCA cells." (PMID 36768755, 2023).
tumor (continued). "However, we did not observe any association between tumor expression of IRS-1 and 2 and survival in our cohort." (PMID 36900240, 2023). "The expression of IRS-1 may further mediate the occurrence of tumor immune escape." (PMID 36245982, 2022). "Likewise, IRS1 downregulation by miRNA-145 inhibited tumor metastasis." (PMID 36140796, 2022). "Notably, we found that 66.2% of tumour samples with p63 up-regulation also exhibited high levels of IRS1 expression A similar correlation was observed in samples with p63 down-regulation, in which 58% of the patients concomitantly displayed low levels of IRS1 transcripts (p-value= 4.293e-07)." (PMID 30594912, 2018). "Moreover, there was a significant correlation between IRS-1 Y612 and the proliferation marker Ki-67 in these ER+ tumours, suggesting that the potential interplay between erbB3, IRS-1 and Akt in these tumours may culminate in driving cell proliferation." (PMID 21939528, 2011). "In conclusion, CREB3 acted as a tumor suppressor in HCC, which inhibited AKT phosphorylation through independently interfering interaction of INSR with IRS1, and transcriptionally activating RBM38." (PMID 38952575, 2024). "Our study reveals the expression pattern and tumour‐promoting role of PYCR1 in LC and identifies the downstream target IRS1 through which PYCR1 promotes LC progression." (PMID 39422696, 2024). "IRS1 is a crucial regulatory factor of PI3K in malignant cells and affects tumor cell proliferation." (PMID 38711992, 2024). "IHC analysis of subcutaneous tumor and lung metastasis tissues also revealed that CREB3 expression was inversely correlated with phosphorylation of IRS1 and AKT." (PMID 38952575, 2024). "In multivariate analyses, high expression of IRS1 in stromal cytoplasm, RUNX3 in tumor nucleus and stromal cytoplasm, and high expression of SMAD4 in tumor and stromal cytoplasm remained independent predictors of improved DSS." (PMID 36900240, 2023). "Many studies have found that IRS-1 negatively regulates tumor progression, whereas IRS-2 promotes tumor behavior through metabolism regulation." (PMID 36831374, 2023). "IRS-1 and 2 and SMAD4 expression was evenly distributed in tumor epithelial cells, spindle shaped cells/stromal cells, and immune cells." (PMID 36900240, 2023). "is normally involved in tumour signalling by dephosphorylation of targets including PTEN itself, insulin receptor substrate 1 (IRS1) and focal adhesion kinase (FAK)." (PMID 36765661, 2023). "Stromal IRS-1 was moderately (0.4 < r < 0.6) correlated with tumor epithelial and stromal SMAD4, and tumor epithelial and stromal RUNX3, indicating a possible link between stromal IRS-1 and pathways involving activated SMAD4 and RUNX3." (PMID 36900240, 2023). "Neutrophil elastase (NE) produced by neutrophils can be endocytosed by tumor cells and then degrade insulin receptor substrate 1(IRS1) to free PI3K bound to IRS1, ultimately promoting tumor proliferation through the PI3K-AKT signal pathway." (PMID 37152022, 2023). "High expression of IRS1 in stromal tissue and RUNX3 and SMAD4 in both stromal and tumor tissue were positive prognostic factors." (PMID 36900240, 2023). "The anticancer microRNA miR-628-5p accelerates tumor suppression in human PDAC, probably by directly targeting the PLSCR1 and insulin receptor substrate 1 (IRS1) genes through inhibition of AKT/NF-κB signal pathways." (PMID 35422844, 2022). "A decrease in IRS-1 levels can enhance the interaction between PI3K and PDGF-R, a factor that promotes tumor cell proliferation." (PMID 36419156, 2022). "TNS2 has been shown to dephosphorylate the insulin receptor substrate 1 (IRS-1) and decrease its activation, which in turn can lead to increased interaction between PI3K and PDGFRA, and thus, increased tumor growth." (PMID 35804982, 2022).
tumor (continued). "Here, we provide several lines of evidence to suggest that PP1, IRS‐1/2, and pRb (p105) are involved in the TGF‐β‐stimulated TβR‐V‐mediated tumor suppressor signaling cascade (TβR‐V/IRS‐2/PP1/pRb)." (PMID 34485840, 2021). "miR-128 was shown to specifically inhibit insulin receptor (INSR) and insulin receptor substrate 1 (IRS1) to abate glycolytic signaling pathway and mitochondrial respiration, resulting in decreased tumor growth." (PMID 33824695, 2021). "Interestingly, H19 had been shown to inhibit Insulin Receptor Substrate 1 (IRS-1), reducing cell viability, migration, and invasion in TC, which supports the thesis that H19 may have a tumor suppressor role in TC cells treated with deacetylase inhibitors, leading to differentiation and cell death." (PMID 34108939, 2021). "The results of WGCNA showed that the turquoise and blue modules, which are highly related to the eutopic endometrial cell group and the ectopic endometrial cell group, all contained tumor related genes, such as UBC, UBA52, RPS27A, PIK3CB, IRS1, and CEACAM1." (PMID 33868805, 2021). "Consistent with this, the protein levels of IRS1 and IGF1R were also decreased in Lv-mir-150 tumor samples from nude mice, as shown by immunohistochemistry analysis." (PMID 33723215, 2021). "The second subpopulation with IRS1 downregulation showed a significant increase in relative inhibitory phosphorylation of IRS1 and TSC2 anti-tumor protein and an increased activation of the mitogenic pathway associated with ERK1/2." (PMID 34684639, 2021). "Overexpression of IRS-1 hyperamplifies IGF signaling and contributes to tumor initiation, progression, and poor cancer prognosis." (PMID 33991522, 2021). "Relative to primary PDX tumours, metastatic lesions expressed abundant p-PR and exhibited an activated PR gene programme with elevated expression of PGR and IRS-1." (PMID 33144693, 2021). "To ascertain if the expression levels of RPS6KB1, RPS6 and IRS-1 proteins varied based on stage of CMM, we used 42 tumor samples (stage I–IV) and 5 normal skin tissues." (PMID 33082316, 2020). "In the same manner, miR-145 exhibits a tumor suppressor activity in CRC by modulating Myc, STAT1 and other genes including IRS-1.In fact, miR-145 downregulation was shown to increase tumor survival, a feature sharply in contrast with the therapeutic success." (PMID 33396628, 2020). "The levels of eight hub genes expression (FN1, CCND1, CDH2, CXCL12, MET, IRS1, DCN and FMOD) in PTC and para-cancerous non-tumor tissues were detected by qRT-PCR." (PMID 32714651, 2020). "Although IRS-1 and IRS-2 share significant homology, they regulate distinct functional outcomes in tumor cells." (PMID 31393907, 2019). "After IRS-1 degradation, an increased interaction between PI3K and PDGFR occurs, thereby skewing the PI3K axis toward tumor cell proliferation." (PMID 31799175, 2019). "MiR-145 can function as a suppressor of cellproliferation and tumor metastasis through targetingmultiple oncogenes such as MYC, Kras, IRS-1, SOX2,MUC1, etc., and its expression level has beenshown in several cancer cell lines." (PMID 29633600, 2018). "To understand the potential mechanism of miR-30e in inhibiting tumor growth, we showed that miR-30e blocked the activation of AKT and ERK1/2 pathways, and the expression of HIF-1α and VEGF via directly targeting IRS1." (PMID 29162879, 2017). "When IRS-1 is overexpressed, the PI3K/AKT pathway becomes constitutively activated, leading to increased cell survival and tumor growth." (PMID 28414818, 2017). "Many potential targets of miR-7 were reported to participate in some important signalling of tumor progression, such as targets EGFR, IRS-1, PAK-1, RAF-1, SATB1, and so on." (PMID 28239300, 2017). "MiR-145 is a well-known tumor suppressor miRNA in CRC targeting the oncogenes ERK5 (mitogen-activated protein kinase 7) and IRS1 (insulin receptor substrate 1); furthermore, its ability to predict survival of CRC patients was also shown." (PMID 29147648, 2017).
tumor (continued). "Taken together, our data demonstrates that IGF-I induces docetaxel resistance and upregulates IGF-IR and IRS1 expression through miR-143 downregulation, whereas miR-143 acts as a tumor suppressor by targeting its targets IGF-IR and IRS1." (PMID 29291019, 2017). "Microarray-based mRNA expression levels confirmed higher expression of IRS1, IGF2, IGF1R and AR in “NFκB off” compared to the “NFκB on” tumours in all five datasets." (PMID 26943587, 2016). "Also under serum depletion with addition of exogenous IGF-1 IRS-1 showed decreased phosphorylation in cells treated with compounds 1 and 2 albeit of less magnitude than when cells were cultured in serum, which was the condition where we found these compounds to have specific anti-tumor activity." (PMID 27384680, 2016). "Other TAZ downstream target genes including IRS-1, MYLK/MLCK, and PLK2 are also important for tumor development and metastasis." (PMID 25940705, 2015). "Neutrophil elastase directly induced lung tumor cell proliferation by degrading IRS-1, which is an adapter protein of PI3K, and subsequently activating the PI3K pathway in the tumor cells." (PMID 26177797, 2015). "Except degradation of IRS-1, NE also cleaves pro-TGF-α to release mature TGF-α in gastric TMK-1 cells, which activates EGFR-induced tumor proliferation." (PMID 24457622, 2014). "Thus, in the present case it seems, the proliferation of tumour cells might be rather supported by increased effect of IGF1, IGF2 and IGF1R homodimer associations, than IGF1, IGF2 and INSR-IGF1R heterodimer associations or INSR effects on IRS1." (PMID 25496518, 2014). "We were also interested in correlating an altered PI3K pathway and a normal PI3K pathway to the NSCLC tumor subtypes ADCA and SCC, gender, smoking status, IRS-1 G972R genotypes as well as to KRAS/BRAF status." (PMID 24500884, 2014). "To mimic the increased expression levels of IRS-1 seen in tumor cells, we established NIH/3T3 cells with stable overexpression of IRS-1." (PMID 22788551, 2012). "For example, mir-145, a known tumor-suppressor-miRNA, was shown to inhibit the IGF1R axis by targeting both IRS-1 and IGF1R." (PMID 22747855, 2012). "All the tumors from single and compound mutants showed IRS1, Akt and Erk 1/2 expression, indicating that IGF signaling is required to maintain tumor growth in vivo." (PMID 20214787, 2010). "High levels of IRS-1, a major signaling molecule downstream of the IGF-1R, are correlated with tumor size and shorter disease-free survival in estrogen receptor-positive breast cancer patients." (PMID 16457688, 2005). "Studies show that upon activation of mTOR, the downstream S6K can phosphorylate insulin receptor substrate 1 (IRS-1), reducing the activity of PI3K and, through negative feedback, attenuating the activity of the PI3K/Akt/mTOR pathway, thereby inhibiting tumor cell activity." (PMID 40704062, 2025). "Other findings reflective of CS1’s higher tumor grade and more aggressive behavior compared with CDS11 cells include the significantly higher mRNA levels of INSULINR, IGF2R, IRS1, NOTCH1, JAGGED1, HES1, and HIF1α, which function to promote tumor cell growth and survival." (PMID 40427168, 2025). "Additionally, silencing of KLF13 raised the protein levels of SH2B1, IRS1, GLUT1, PDK1, and LDHA in xenograft tumours, and KLF13 overexpression exhibited the reverse actions." (PMID 41410190, 2025). "Furthermore, miR‐3126‐5p, SH2B1, and IRS1 levels were elevated, but KLF13 level was reduced in tumours of Exos‐treated mice, whereas KLF13 overexpression counteracted these changes, except change in miR‐3126‐5p expression." (PMID 41410190, 2025). "Also, IF staining revealed that CREB3 overexpression decreased IRS1 colocalization with INSR in HLF cells and LM3 cells, as well as in HLF subcutaneous tumor tissues." (PMID 38952575, 2024).